DICER1 (dicer 1, ribonuclease III)
Diseases named in the same sentence as DICER1 in open-access papers (continued):
Sharing a sentence is not in itself a finding about the gene and the disease.
cancer (continued). "We report a range of DICER1 pathogenic variant prevalence in adult and pediatric cancer populations drawn from large publicly available datasets." (PMID 30672147, 2019). "Overall, these integrated analysis of cancer genome, small RNA, and transcriptome profiling reveal tissue-specific accumulation of DICER1 RNase III hotspot mutations, including an allele within the RNase IIIa domain that affects RNase IIIb function." (PMID 31417090, 2019). "Accordingly, cancer-associated DICER1 hotspot mutations bias the relative yield of 5p to 3p miRNAs in tumors." (PMID 31417090, 2019). "In a recent survey of cancer cell lines, it was reported that 4 of 781 of these lines presented a DICER1 truncating mutation." (PMID 29459759, 2018). "A recent survey of cancer cell lines showed that 4 of 781 of these lines presented a DICER1 truncating mutation." (PMID 29459759, 2018). "Nevertheless, we were able to validate expressed mutations in two previously reported cancer drivers: DICER1 and NF1." (PMID 29459759, 2018). "This pedigree demonstrates that genetic alteration in the DICER1 gene can cause a wide clinical spectrum of carcinomas, in accordance with recent studies." (PMID 28222777, 2017). "For the rs1057035 T>C variant in DICER1, a significant (13%) increase in cancer risk was found in the overall pooled analysis (AA vs. AC + CC: OR 1.13, 95% CI [1.05–1.22])." (PMID 27957388, 2016). "In summary, this meta-analysis suggests a potential role of the miRNA biogenesis genes DGCR8 (rs417309 G>A) and DICER1 (rs1057035 T>C) in cancer risk." (PMID 27957388, 2016). "The variation of DICER1 were correlated with cancer risk through affecting cell proliferation and apoptosis all those component are key enzymes in miRNAs mature process." (PMID 27957388, 2016). "In this study, a meta-analysis was conducted to evaluate the association between SNPs in five genes (DROSHA, DGCR8, XPO5, RAN, and DICER1) involved in the canonical microRNA biogenesis pathway and human cancer risk." (PMID 27957388, 2016). "The results demonstrated that the GG genotype of rs417309 in DGCR8 was significantly rarer among cases compared with controls in the overall pooled analysis and the TT genotype of rs1057035 in DICER1 was associated with a 13% increase in cancer risk." (PMID 27957388, 2016). "Significant associations were observed between cancer risk and the DGCR8polymorphism rs417309 G >A (OR 1.22, 95% CI [1.04–1.42]), as well as the DICER1 polymorphism rs1057035 TT (OR 1.13, 95% CI [1.05–1.22])." (PMID 27957388, 2016). "It has been established, that reduced expression of DICER1 is associated with a poor cancer outcome." (PMID 27473538, 2016). "In other cancers, low expression of DICER1 has been associated with inactivating DICER1 mutations and miR-107/103 deregulation." (PMID 26087193, 2015). "DICER1 is an enzyme responsible for the cleavage of miRNA precursors and has previously been implicated in the oncogenic process of several cancers." (PMID 26688807, 2015). "In view of these previous studies, we wished to establish if germ-line DICER1 mutations play a role in the etiology of TGCT, with the clinical aim of better counselling DICER1 mutation carriers as to their cancer risks." (PMID 23547758, 2013). "Germline DICER1 mutations have also been described in a number of other rare cancers that occur in children, such cervical embryonal rhabdomyosarcoma and pituitary blastoma." (PMID 23641362, 2013). "The inhibition of Dicer1 activity on its own has also been associated with cancer development, invasion and lymph node metastasis." (PMID 22716183, 2012). "The significance of mutations in DROSHA and DICER1 in cancer was extensively reviewed." (PMID 40243428, 2025). "DICER1 plays a crucial role in regulating RNA processing, the maturation of small non-coding RNAs, and RNA-mediated gene silencing; therefore, it is not unexpected that the DICER1 gene is often mutated in a variety of cancers." (PMID 40361440, 2025).
cancer (continued). "Relevant literature indicates that the occurrence of such tumors is closely related to DICER1 gene mutations, which may increase susceptibility to various benign and malignant tumors." (PMID 40901169, 2025). "DICER1 germline mutations outside hotspot regions, and a “second hit” - somatic mutations in the DICER1 RNase IIIb domain, contribute to the development of both benign and malignant tumors." (PMID 40007992, 2025). "Mutations in Dicer1, although rare, have been shown to be implicated in cancer development." (PMID 41002430, 2025). "Germline DICER1 PVs increase an individual’s risk for benign and malignant tumors." (PMID 40634537, 2025). "However, the molecular results revealed one case with a pathogenic MSH6 mutation along with two common cancer-driver mutations in DICER1." (PMID 39592485, 2025). "Their study showed that mutations in DICER1 were linked to several types of cancer and may represent a novel carcinogenic pathway." (PMID 38836981, 2024). "In addition to these therapeutically actionable variants, DICER1 alterations were present in 4% (13/313) of the rare diagnoses, with potential implications for both diagnosis and germline cancer predisposition." (PMID 38992034, 2024). "Moreover, our obtained MSA was applied for analysis of those DICER1 variants that occurred in cancer where the role of this gene is of particular interest." (PMID 39421690, 2024). "Because Dicer was suggested to have a putative role in hematological malignancies, we examined variants of DICER1 occurring outside the well-known hotspots of the RNase III domain in this type of cancer using phylogenetic reconstruction of individual domain history." (PMID 39421690, 2024). "The DICER1 gene and its mutations draw interest from the carcinogenesis perspective as a crucial and irreplaceable player in miRNA and the siRNA biogenesis gene, while cancer pathogenesis is widely characterized by the dysfunction of the miRNA spectrum." (PMID 39421690, 2024). "Heterozygous mutations in Dicer1 are recurrent in diverse cancers." (PMID 39409030, 2024). "Among them, only six cancer-associated Dicer1 hotspots have been reported previously." (PMID 39421690, 2024). "Recent studies have demonstrated an underlying link between cancer stemness and Dicer1." (PMID 38836981, 2024). "To overcome problems associated with the use of automated variant predictors, we constructed our own datasets of well-defined Dicer1 orthologs based on its evolutionary history and domain architecture and used these datasets to derive a risk map for DICER1-associated cancer." (PMID 39421690, 2024). "Mutation of DICER1 results in the susceptibility to a variety of malignant tumors." (PMID 37461056, 2023). "Notably, germline variants in DICER1 have long been recognized to confer genetic susceptibility to develop cancers, including RMS." (PMID 37345159, 2023). "In addition, there is increasing evidence that germline DICER1 pathogenic variants are associated with lower penetrance for cancer than previously assumed." (PMID 34170462, 2021). "To avoid potential biases associated with pan-cancer normalization, we performed expression analysis separately for UCEC, which is the cancer type with the most frequent mutations in DICER1 (∼9%), with 2 mutations in RIIIa, 10 mutations in RIIIb and 9 deleterious mutations." (PMID 33406242, 2021). "However, DICER1 mutations are also associated with well-differentiated carcinomas in the pediatric population." (PMID 33543394, 2021). "Dicer1 syndrome—also known as pleuropulmonary blastoma familial susceptibility syndrome—is a rare genetic disorder that is inherited in an autosomal dominant manner and predisposes the development of both benign and malignant tumors." (PMID 33007856, 2020). "Notably, there, the gene DICER1 is located, recently identified as playing a role in cancer predisposition." (PMID 32630352, 2020). "This indicates a dearth of DICER1 hotspot mutations across the vast majority of cancer types." (PMID 31417090, 2019).
cancer (continued). "In addition, although large numbers of somatic DICER1 mutations appear in cancer genome sequencing, it is relevant to know if additional driver alleles beyond RNase IIIb hotspots can be distinguished." (PMID 31417090, 2019). "However, other studies indicate that DICER1 hotspot mutations are biallelic in cancer, and act in trans to nonsense or inactivating alleles of DICER120,21,37." (PMID 31417090, 2019). "This suggests that these germline mutations in DICER1 have been associated with cancer." (PMID 30306785, 2018). "Compelling evidence suggests that alterations in DICER1 levels or activity may be important for other age‐associated diseases, especially cancer." (PMID 26990999, 2016). "Analysis of associations between SNPs from DROSHA, DGCR8, XPO5, RAN, and DICER1 and cancer risk." (PMID 27957388, 2016). "Low DICER1 expression was associated with poor outcome in several cancers." (PMID 26087193, 2015). "Moreover, we report, for the first time in PTC, somatic mutations in cancer driver genes (DICER1, MET and VHL) described in other tumors." (PMID 25803323, 2015). "Notably, WNK1-B4GALNT3 positive patient also carries a somatic mutation in DICER1, cancer driver gene." (PMID 25803323, 2015). "Despite a detailed study of hundreds of cancer cell lines, the full extent and limit of the involvement of both germ-line and somatic DICER1 mutations in rarer types of human cancer is currently unknown." (PMID 23547758, 2013). "A number of previous studies have shown that DICER1 mutations are found in <1% of most cancers." (PMID 23068969, 2012). "In addition to mutations, aberrant expression of Dicer1 has also been observed in cancer." (PMID 41002430, 2025). "Moreover, they may help explain why cancer-associated DICER1 mutations predominantly affect RNase IIIb activity rather than RNase IIIa." (PMID 41188596, 2025). "Indeed, both germline and somatic mutations in DICER1 were identified in diverse types of cancer." (PMID 39421690, 2024). "Moreover, various new somatic DICER1 mutations continuously appear in cancer genome sequencing." (PMID 39421690, 2024). "The estimated prevalence of pathogenic DICER1 variants in the general population is ~1:10,600, and approximately 30,000 Americans harbor pathogenic DICER1 mutations; however, this prevalence is seemingly higher and is estimated at ~1:4600 in the adult cancer population." (PMID 34599283, 2022). "Therefore, DICER1 mutations may represent “Early” events in this specific population whereas progression to poorly differentiated carcinoma may be associated to additional “Late” events, in a model similar to the adult counterpart." (PMID 33543394, 2021). "The encoding genes of the major DROSHA, DGCR8, and DICER1 components are frequently up-regulated in many solid tumors which modify the global miRNA expression profile and contribute to the main attributes of cancer progression, such as increased cell proliferation, migration and invasion." (PMID 31683635, 2019). "Indeed, lower levels of DICER1 mRNA have been associated with decreased cancer survival." (PMID 26688807, 2015). "Thus, one can hypothesize that a selective pressure operating in cancer cells acts against complete loss of DICER1 and supports the appearance of specific mutations that are not deleterious for the encoded protein." (PMID 25883138, 2015). "Thus, it may be possible to adopt similar strategies for overcoming cancer-associated mutations in DICER1 or FOXL2." (PMID 23641362, 2013). "Pathogenic or likely pathogenic variants in cancer-associated genes were identified in 37 (6.8%), most frequently in MITF, DICER1, and BRCA2, while 43 (7.9%) harbored variants in NDD-related genes, including DHCR7, POLG, and ARSA." (PMID 41844650, 2026). "Intracranial tumors are prone to complex changes similar to malignant peripheral nerve sheath tumors, while urogenital sites are more likely to develop DICER1 alteration-related MEM, and other sites exhibit changes more closely resembling ERMS and ARMS." (PMID 41465905, 2025).
cancer (continued). "Aberrant expression of Dicer1 contributes to a wide range of human pathologies, including cancer, making Dicer1 an attractive target not only for cancer but also for other pathologies." (PMID 41002430, 2025). "Through its involvement in post-transcriptional regulation, DICER1 influences various biological processes, including embryogenesis and cellular differentiation, and is therefore frequently deregulated in cancer." (PMID 40361440, 2025). "Pathogenic germline DICER1 variants were described as the genetic basis of PPB and later associated with a spectrum of benign and malignant neoplasms affecting mostly children and adolescents." (PMID 40150037, 2025). "All seven tumors showed widespread, intense reactivity (3 + to 4 +), with stronger DICER1 expression in carcinomas and larger tumors than in the surrounding parenchyma." (PMID 40448797, 2025). "Advances in understanding the genetic and molecular functions of Dicer1 have opened new horizons into its role in cancer progression with questions that remain unanswered." (PMID 39421690, 2024). "Advances in understanding the genetic and molecular functions of Dicer1 have led to new insights into its role in cancer progression." (PMID 39421690, 2024). "The influence of Dicer1 and cancer stem cells goes beyond mere manipulation of cell mobility and lifespan." (PMID 38836981, 2024). "Dicer1 heterozygous tumors can show partial DNA damage response and therefore increased mutagenesis frequency, promoting cancer progression." (PMID 39409030, 2024). "Recent revelations of hotspot tumors linked to DICER1 in both PPB and PPB-FTDS patients who possess hereditary DICER1 mutations offer compelling support for the two-hit theory of cancer development." (PMID 38836981, 2024). "In the pan-cancer study, average mutation rates ranged from 0.23% for the RAN gene to 1.87% for the DICER1 gene." (PMID 36672288, 2023). "These subclones harbored putative metastasis-driving mutations in cancer-related genes such as SMAD4, ROBO1, and DICER1." (PMID 36476508, 2022). "In particular, we demonstrated that by regulating miR-33a and miR-130b expression levels, APE1 modulates DICER1 expression in cancer cell lines." (PMID 35876890, 2022). "Genetic variants of unclear significance were however detected in genes such as CDH1, DICER1, MEN1, RET, CREBBP, RAD51C, or SOS1, which are linked to autosomal dominant predisposition to cancer." (PMID 35250968, 2022). "It means that the mRNA expression levels of cancer genes are increased in Dicer1 KO mESCs, and the elevation degree is significantly higher than total protein-coding genes, whose log2 fold change of KO/WT was about zero." (PMID 35328035, 2022). "It showed that the log2 fold change of 733 cancer genes between Dicer1 KO and WT was higher than zero, and significantly higher than total protein-coding genes (p-value < 2.2 × 10−16)." (PMID 35328035, 2022). "Several known cancer-associated genes are located on 14q, including CHD8, FOXA1, HIF1A, and DICER1, encoding proteins involved in DNA damage/response, hypoxia response, and miRNA processing, respectively." (PMID 34205964, 2021). "For example, germline and somatic mutations in DROSHA, DGCR8, DICER1, and XPO5 genes have been identified in several cancers, including Wilms tumors, pleuro-pulmonary blastoma, non-epithelial ovarian cancer, endometrial, colon, and gastric tumors." (PMID 34573429, 2021). "Several studies have been carried out on different types of cancer to clarify the role of Dicer1 in carcinogenesis and its impact on prognosis." (PMID 33763118, 2021).